CSF1 (colony stimulating factor 1)
Diseases named in the same sentence as CSF1 in open-access papers (continued):
Sharing a sentence is not in itself a finding about the gene and the disease.
glioma (114 papers, 2009 to 2026). A benign or malignant brain and spinal cord tumor that arises from glial cells (astrocytes, oligodendrocytes, ependymal cells). "DHX9 silencing decreased the expression of colony‐stimulating factor 1 (CSF1), which partially restored the inhibitory effect on malignant progress of glioma and infiltration of TAMs caused by DHX9 knockdown by targeting the transcription factor 12 (TCF12)." (PMID 36377508, 2023). "Although these findings suggest that CSF-1 and IL-34 are susceptible to regulation, anti-CSF-1R therapy warrants further study for effective use in glioma treatment." (PMID 37153567, 2023). "We also confirmed the target association between miR‐1254 and established CSF‐1 knockdown as well as overexpressing cells to determine its impact on cellular processes in glioma." (PMID 31994318, 2020). "This study strived to evaluate the association between CSF‐1 and miR‐1254 and their effect on advancement of glioma cells." (PMID 31994318, 2020). "We determined the miR‐1254 levels in glioma samples and assessed the relationship between miR‐1254 and CSF‐1 to evaluate its association with progression of glioma cells." (PMID 31994318, 2020). "Epidermal growth factor (EGF) and colony-stimulating factor-1 (CSF-1) have also been implicated in TAM glioma crosstalk." (PMID 31231208, 2019). "A paracrine CSF1-EGF signaling loop implicated in glioma invasion has been established between glioma cells and TAMs." (PMID 27385209, 2016). "GBMs with poor prognosis contain high numbers of tumor-associated macrophages (TAM), recruited to the glioma microenvironment by CSF1 expressed by the glioma cells." (PMID 27385209, 2016). "In support of this, Csf1 was the gene most frequently insertionally mutated in Rosa26-SB11 gliomas in both this and our previous study." (PMID 25423036, 2014). "Our investigation revealed a positive correlation between the expression of CLEC7A and monocyte chemoattractant factors (CCL2, CCL5) as well as factors implicated in M2 macrophage polarization (TGF-β1, CSF-1) in glioma samples obtained from both TCGA and CGGA databases." (PMID 38846954, 2024). "There is an association of oncogenic pathways and higher glioma grades with CSF-1 expression." (PMID 37345193, 2023). "As Csf1 was the gene insertionally mutated the most frequently in our previous SB glioma screen, we hypothesized that identification of additional glioma genes would be facilitated on a Csf1 deficient or heterozygous background." (PMID 25423036, 2014). "Circulating monocytes are recruited in gliomas via several growth factors and chemokines (like CSF-1, CCL2, CCL7, CCL20)." (PMID 41157253, 2025). "Given the central role of TAMs in tumor biology, targeting either CSF-1 or its receptor has been suggested as a therapeutic strategy for gliomas and other tumors." (PMID 40845580, 2025). "In the glioma microenvironment, there is a high presence of inflammatory mediators and chemotactic substances, including colony-stimulating figure (CSF-1, -2) and glial cell-derived neurotrophic figure (GDNF)." (PMID 40727443, 2025). "Glioma progression and microglial activation are induced by tumor-derived macrophage colony-stimulating factor (M-CSF, CSF1) and granulocyte-macrophage colony-stimulating factor (GM-CSF, CSF2)." (PMID 40727443, 2025). "This highlights the instrumental role of glioma-derived CSF1 and IL-34 in the differentiation of M-MDSCs, as blocking the CSF1R axis prevents expansion of the M-MDSC population in whole bone marrow." (PMID 39272914, 2024). "CSF1 has been shown to be produced directly by glioma cells and works by binding to the CSF1 receptor (CSF1R) to regulate monocyte and microglial migration and promote TAM polarization towards the M2 phenotype." (PMID 38893093, 2024). "Studies focusing on microglia and macrophages have revealed their reactions to Glioma-derived Colony-Stimulating Factor-1 (CSF-1) through the use of mouse models, human GBM tumor spheres, and cell lines." (PMID 38534769, 2024).
glioma (continued). "We also found that CSF-1, CSF-2, and CSF-3 were all differentially upregulated in the murine glioma microenvironment." (PMID 39272914, 2024). "Perhaps the most promising approach in this instance is CSF-1 inhibition, which has been shown to reduce glioma recurrence after radiation in vivo." (PMID 37345193, 2023). "We have previously shown that the CSF-1/CSF-1R axis is critical for microglia stimulated glioma invasion using both the coculture in-vitro assay and using syngeneic C57BL/6 mouse model." (PMID 36982211, 2023). "While CSF-1R, CSF-1 and IL-34 directly support tumor cell growth, CSF-1, highly expressed by glioma cells, effectively promotes macrophage recruitment and indirectly promotes malignant pathogenesis via GAM interactions." (PMID 37153567, 2023). "With the aid of the anti-inflammatory cytokines and CSF-1 secreted by both microglia and glioma cells, infiltrating monocytes can differentiate into BMDM and polarize toward a M2 phenotype." (PMID 37345193, 2023). "In the current study, we showed that CSF1 can abolish the inhibitory effect of DHX9 silencing behind the proliferation, migration, and invasion of glioma cells and infiltration of TAMs in vivo, which implied that CSF1 was the functional target of DHX9." (PMID 36377508, 2023). "In both LGG and GBM, ZBTB42 was positively related to CSF1, which is known for promoting glioma immune suppression." (PMID 36762114, 2023). "Simultaneously, compared to TAMs cocultured with DHX9‐silenced glioma cells, the proliferative capacity of TAMs was higher in si‐DHX9 with CSF1‐overexpression plasmid‐transfected glioma cells." (PMID 36377508, 2023). "There is an article confirms that DHX9 can increase TAM infiltration in glioma by regulating the TCF12/CSF1 axis, and then promote its polarization into M2 Macrophage, which finally promote the progression of GBM." (PMID 37602882, 2023). "Next, to investigate the role of CSF1 in DHX9‐mediated glioma progression and TAMs infiltration, A172 and LN229 cells were transfected with NC, si‐DHX9 alone, or si‐DHX9 with CSF1‐overexpression plasmids." (PMID 36377508, 2023). "One study of the SETDB1 enzyme revealed significantly increased expression in glioma and resultant promotion of CSF-1 secretion via AKT/mTOR signaling, thereby enhancing macrophage recruitment and polarization." (PMID 37153567, 2023). "Glioma cells release a range of chemokines (CSF-1, MCP-1 and others) to recruit and activate TAMs, which then secrete the anti-inflammatory cytokines IL-10 and TGFB1." (PMID 37837549, 2023). "Colony-stimulating factor 1 produced by glioma has been proved to polarise macrophages into the M2 phenotype supported by glioma, thus promoting the progression of glioma." (PMID 37273917, 2023). "Due to the anti-inflammatory environment in gliomas, and the secretion of CSF-1 in the TME, microglia predominantly polarize towards M2 phenotype." (PMID 37345193, 2023). "Glioma progression is also supported by astrocytic release of CC chemokine ligand 2 (CCL2) and colony-stimulating factor 1 (CSF1), leading to recruitment of tumor-associated macrophages with a pro-tumor phenotype." (PMID 38275375, 2023). "Some studies also reported that CSF1 promotes tumor growth and infiltration of TAMs in gliomas;32, 33 however, the regulatory network remained unclear." (PMID 36377508, 2023). "Colony-stimulating factor-1 (CSF-1) is able promote the function and survival of small glioma cells and TAMs, and the inhibition of the CSF-1 receptor (CSF-1R) relieves TME immunosuppression by depleting TAMs and synergizes with other immunotherapies." (PMID 35833121, 2022). "CSF-1 secreted by glioma cells is essential for the differentiation and survival of TAMs and facilitates M2 polarization of TAMs." (PMID 35967394, 2022). "Glioma-derived cytokines such as the colony stimulating factor 1 and 2 (CSF1/2) stimulate infiltration of GAMs and promote an M2 anti-inflammatory, pro-tumoral phenotype." (PMID 36186781, 2022).
glioma (continued). "In glioma, BMDMs and microglia accumulate in tumor tissue attracted by chemokines, such as CSF1 and CCL2, secreted by tumor cells and constitute the glioma-associated macrophages/microglia (GAM)." (PMID 35494072, 2022). "High levels of CSF-1 and CSF-1R have been observed in high-grade human glioma, supporting their pivotal role in tumour growth." (PMID 34950148, 2021). "These glioma-associated microglia and MΦ (GAM) are recruited by glioma cells, secreting several chemoattractants such as CCL2, Cx3CL1, SDF-1, and CSF-1, among others." (PMID 34445160, 2021). "Gliomas produce other factors that signal to macrophage lineage cells, so one possible explanation is that increased levels of CSF1 alone are unable to increase expression of M2 polarization genes but can do so when combined with other signals." (PMID 34281564, 2021). "Similar to CSF-1, granulocyte–macrophage colony stimulating factor (GM-CSF) is a key molecule promoting microglial proliferation and glioma progression." (PMID 34884869, 2021). "That study showed that CSF-1 is expressed by GL261 glioma cells and the receptor CSF-1R is expressed by microglia, thus defining a paracrine interaction that takes place between glioma and microglia during invasion." (PMID 34843542, 2021). "M2 polarization was also induced by metabolites of glioma cells such as adenosine, along with the secretion of CSF-1, the expression of CCR5, and DNA damage repair of glioma cells." (PMID 34211978, 2021). "Glioma cells release several factors, such as colony‐stimulating factor 1 (CSF‐1), glial‐derived neurotrophic factor and granulocyte‐macrophage colony‐stimulating factor, to attract TAMs to the tumour site." (PMID 32969157, 2020). "This was further confirmed by western blotting that the seven glioma cell lines exhibited much high levels of CSF‐1 than that in normal cell NHAs." (PMID 31994318, 2020). "In the recent study, miR-532-5p was discovered to have inhibitory function in glioma cells via targeting CSF1." (PMID 32249890, 2020). "The CSF‐1 down‐regulation or miR‐1254 overexpression impeded the invasion, proliferation and migratory ability of U251 and U87 glioma cells, concurrently occluded the cell cycle and induced cell apoptosis." (PMID 31994318, 2020). "We found significantly enhanced CSF‐1 expression in glioma specimens, and also showed both in vitro and in vivo, that increased expression of miR‐1254 repressed CSF‐1 level, indicating an inverse relationship between them." (PMID 31994318, 2020). "Considering these in conjunction, as per these findings miR‐1254 has a vital role in inhibiting proliferation of glioma cells via the CSF‐1 suppression." (PMID 31994318, 2020). "The results of CCK‐8 show that the glioma cell viability was more robust in the CSF‐1 overexpression group but was significantly reduced in the group with CSF‐1 knockdown compared to that in the mock group." (PMID 31994318, 2020). "To assess the correlation between miR‐1254 and CSF‐1 expressions in gliomas, we carried out Western blotting to determine CSF‐1 levels in NBTs, grade II and grade III, as well as GBM glioma samples." (PMID 31994318, 2020). "These tumor-associated microglia (TAM) involved in CSF-1, STI1, and especially TGFβ signaling, are reported to suppress immune response and promote glioma growth." (PMID 32974124, 2020). "Since colony stimulating factor-1 (CSF-1) secreted by glioma cells is a driver of differentiation, polarization, survival, and recruitment of TAMs, strategies aimed at targeting the CSF-1 receptor (CSF-1R) on TAMs have been extensively investigated." (PMID 33374253, 2020). "As per real‐time PCR results the expression of CSF‐1 in glioma cells A172, H4, U87, U118 and U251 and was remarkably higher compared with that in normal NHAs cells." (PMID 31994318, 2020). "We found in both glioma tissues and glioma cells, the down‐regulated expressions of miR‐1254 while that of CSF‐1 was abnormally higher than normal level." (PMID 31994318, 2020).
glioma (continued). "We also confirmed CSF‐1 as the direct target of miR‐1254 through dual‐luciferase reporter assay, and that overexpression of CSF‐1 invigorated viability and metastasis of glioma cells." (PMID 31994318, 2020). "Glioma-derived CSF-1, also known as macrophage colony-stimulating factor, induces a shift of microglia/macrophages toward M2-type TAMs, which enhance tumor growth." (PMID 32823915, 2020). "The microglial-released EGF increases tumor invasion by activating its receptors on GBM cells, while CSF-1 secreted by glioma acts as a chemoattractant for TAMs." (PMID 31231208, 2019). "Immunoblot analysis confirmed that glioma-CM remarkedly increased IL-6 expression and moderately increased CSF-1 expression in ECs, and also showed that GBM-associated ECs constitutively expressed IL-6 and CSF-1 at a higher level than normal brain ECs." (PMID 29422647, 2018). "In this review, the colony-stimulating factor 1 receptor (CSF-1R) ligand CSF-1 (M-CSF) is secreted by glioma cells and facilitates the recruitment and M2 polarization of GAMs." (PMID 29389898, 2018). "Colony stimulating factor-1 (CSF-1) is released by glioma cells and acts as a microglial chemoattractant." (PMID 30319362, 2018). "M1 and M2 types of microglia were shown to promote glioma cell invasion by exchanging signaling molecules such as CSF-1, EGF and TGF-β." (PMID 30286133, 2018). "Attenuated interactions between CSF-1 and CSF-1R with CSF-1R-targeting inhibitors reduce the number of TAMs in tumor sites and impair the invasion ability of glioma cells." (PMID 30619286, 2018). "One interaction of potential therapeutic interest in glioma is the macrophage proliferation cytokine CSF1 and its cognate receptor CSF1R, which has been extensively validated in pre-clinical studies in glioma along with its potential therapeutic efficacy." (PMID 30041684, 2018). "Macrophages also critically depend on the multiple functions of CSF-1, which is constitutively expressed by glioma cells, facilitated by its receptor CSF-1R." (PMID 30619286, 2018). "Glioma cells also release M-CSF (CSF-1), which markedly promotes GAM motility and converts microglia into the pro-tumorigenic M2-like phenotype." (PMID 29389898, 2018). "CSF-1 inhibitors have shown to deter glioma recurrence after radiation in vivo, prevent radiation-induced cognitive impairment in preclinical models, and are well-tolerated in clinical trials." (PMID 30467536, 2018). "In order to understand the potential of anti‐macrophage therapy concerning blood vessel function and glioma progression, we inhibited macrophage recruitment in the tumor microenvironment using anti‐CSF1 monoclonal antibody treatment." (PMID 29038312, 2017). "At late‐stage growth (4 weeks), Glut1 and CD31 immunostaining revealed a profound “normalization” of blood vessel parameters in anti‐CSF1 antibody‐treated glioma‐bearing mice compared to isotype‐matched control antibody treatment." (PMID 29038312, 2017). "Strikingly, both TAM depletion and macrophage‐specific VEGF deletion accelerated tumor growth significantly, and conversely, treatment with recombinant CSF‐1 delayed glioma growth while accelerating the vessel dysmorphia." (PMID 29127101, 2017). "Nonetheless, gliomas are also known to secrete chemoattractant molecules (e.g., CSF1, SDF1, CX3CL1) that attract microglia/macrophages." (PMID 28098415, 2017). "Administration of a monoclonal antibody macrophage inhibitor targeting CSF1 maintains a functional and highly branched vasculature until the late‐stage glioma." (PMID 29038312, 2017). "To further investigate the effects of macrophage accumulation on glioma vessel parameters, we treated early‐stage tumor‐bearing mice (3 weeks) with recombinant‐CSF1 protein." (PMID 29038312, 2017).
glioma (continued). "To investigate the relevance of our findings in a therapeutic treatment‐based approach, we performed survival experiments combining temozolomide (TMZ) recommended chemotherapeutic agent for glioma treatment and anti‐CSF1 monoclonal antibody treatment." (PMID 29038312, 2017). "CSF1, constitutively released by the glioma cells, acts as a chemoattractant for microglia and also converts microglia into a protumorigenic phenotype." (PMID 29410971, 2017). "Interfering with CSF1 signaling by antibody-mediated blockade or use of CSF1R inhibitors is a potential approach to regulate glioma growth by targeting TAMs." (PMID 29410971, 2017). "Previous qRT-PCR and immunohistochemical analyses have detected increased levels of CSF1 in human high-grade gliomas." (PMID 25423036, 2014). "In this study, the glioma from a Csf1 heterozygous mouse also harbored an insertion in Csf1, indicating a strong selective pressure for Csf1 up-regulation during Rosa26-SB11-driven gliomagenesis." (PMID 25423036, 2014). "We, and others, have demonstrated high levels of CSF1 mRNA and protein in human gliomas and we present here that both genetic and epigenetic changes occur at the CSF1 locus in human GBM." (PMID 25423036, 2014). "Glioma cells constitutively express colony stimulating factor-1 (CSF-1) that stimulates microglia invasion through its receptor CSF-1R." (PMID 23864876, 2013). "Immunosuppressive properties of glioma cancer stem cells, producing CSF-1, TGF-β1 and macrophage inhibitory cytokine, and inducing polarisation of recruited macrophages/microglia have been demonstrated." (PMID 21901144, 2011). "Glioma-derived CSF-1 not only acts as chemoattractant but also induces a shift of microglia and macrophages toward a pro-tumor phenotype, and blocking CSF-1 receptor (CSF-1R) inhibits alternative activation of TAMs and attenuates glioma progression." (PMID 38254796, 2024). "Colony Stimulating Factor-1 (CSF-1) has been shown to be especially important in mediating this interaction within glioma tumors and blockade of CSF-1/CSF-1R pathway has been very effective preventing metastatic progression in many different preclinical cancer models." (PMID 36982211, 2023). "In the correlation analysis, ZBTB42 is positively related to the expression of CSF-1 in both LGG and GBM indicating ZBTB42 is associated with immune suppression in glioma and this feature may be related to the increased expression of CSF-1." (PMID 36762114, 2023). "Tumor-associated microglia promoting glioma cell invasion can be mediated by CSF-1R signaling on gliomas, a pathway involving CSF-1 signaling via ERK that upregulates the expression of dual-regulatory proteins (AREG) in microglia, which are ligands for epithelial growth factor receptor (EGFR)." (PMID 37700840, 2023). "Furthermore, TCF12 knockdown eliminated the carcinogenic effect caused by DHX9 overexpression, suggesting that DHX9 promoted the CSF1‐induced glioma growth and recruitment of TAMs in a TCF12‐dependent manner." (PMID 36377508, 2023). "The mechanistic investigations showed that DHX9 promote glioma progress by targeting the TCF12/CSF1 axis, indicating that DHX9 might be a novel target for precise immunotherapies against gliomas." (PMID 36377508, 2023). "DHX9/TCF12/CSF1 axis regulate the infiltration of TAMs to promote glioma progression and may be a novel potential target for future immune therapies against gliomas." (PMID 36377508, 2023). "CSF-1 secreted by glioma cells acts on CSF-1R on microglia, which attracts microglia to the tumor and induces a shift to a pro-tumorigenic phenotype, enhancing the crosstalk between microglia and glioma." (PMID 37700840, 2023). "CSF-1 secreted by glioma cells can also support the recruitment of TAMs." (PMID 35967394, 2022).